KRTAP20-1 (keratin associated protein 20-1)
Description:
In the hair cortex, hair keratin intermediate filaments are embedded in an interfilamentous matrix, consisting of hair keratin-associated proteins (KRTAP), which are essential for the formation of a rigid and resistant hair shaft through their extensive disulfide bond cross-linking with abundant cysteine residues of hair keratins. The matrix proteins include the high-sulfur and high-glycine-tyrosine keratins.
Synonyms: KAP20.1
Tractability: No criterion of Open Targets' tractability assessment is met for any kind of drug.
Gene: Protein-coding gene on chromosome 21 (30,616,425 to 30,616,699, forward strand). Ensembl gene ENSG00000244624.
Pathways (Reactome):
Developmental Biology: Keratinization
Gene Ontology:
Cellular component: cytosol
Genetic constraint (gnomAD): Loss-of-function variants: 6 observed, 4.02 expected, observed/expected ratio (o/e) 1.49, 90% interval 0.75 to 1.93. That is too few expected variants to judge how well the gene tolerates losing a copy. Missense variants: 30 observed, 29.79 expected, observed/expected ratio (o/e) 1.01, 90% interval 0.75 to 1.37. Synonymous variants: 14 observed, 11.29 expected, observed/expected ratio (o/e) 1.24, 90% interval 0.81 to 1.82.
Homologues: Orthologues: chimpanzee KRTAP20-1 (98% identical), rabbit KRTAP20-1 (75% identical).